GON7 (GON7 subunit of KEOPS complex)
Description:
Component of the EKC/KEOPS complex that is required for the formation of a threonylcarbamoyl group on adenosine at position 37 (t(6)A37) in tRNAs that read codons beginning with adenine. The complex is probably involved in the transfer of the threonylcarbamoyl moiety of threonylcarbamoyl-AMP (TC-AMP) to the N6 group of A37. GON7 plays a supporting role to the catalytic subunit OSGEP in the complex.
Synonyms: C14orf142; PNAS-127
Tractability: No criterion of Open Targets' tractability assessment is met for any kind of drug.
Gene: Protein-coding gene on chromosome 14 (93,202,890 to 93,207,068, reverse strand). Ensembl gene ENSG00000170270.
Subcellular location: Nucleus
Subcellular location (Human Protein Atlas): Nucleoli rim; Nucleoplasm
Pathways (Reactome):
Metabolism of RNA: tRNA modification in the nucleus and cytosol
Gene Ontology:
Molecular function: protein binding
Biological process: tRNA threonylcarbamoyladenosine modification; maintenance of translational fidelity
Cellular component: EKC/KEOPS complex; nucleolus; nucleoplasm; nucleus
Genetic constraint (gnomAD): Loss-of-function variants: 2 observed, 7.06 expected, observed/expected ratio (o/e) 0.28, 90% interval 0.12 to 0.89. That is too few expected variants to judge how well the gene tolerates losing a copy. Missense variants: 113 observed, 134.27 expected, observed/expected ratio (o/e) 0.84, 90% interval 0.72 to 0.98. Synonymous variants: 51 observed, 57.87 expected, observed/expected ratio (o/e) 0.88, 90% interval 0.7 to 1.11.
Homologues: Orthologues: chimpanzee GON7 (97% identical), macaque GON7 (94% identical), pig GON7 (78% identical), guinea pig GON7 (66% identical), mouse Gon7 (64% identical).
Diseases named in the same sentence as GON7 in open-access papers:
GON7 is named in the same sentence as 13 diseases in open-access papers, as found by Europe PMC text mining. Sharing a sentence is not in itself a finding about the gene and the disease. The quoted sentences say what the papers report.
Galloway-Mowat syndrome (3 papers, 2019 to 2023). Galloway syndrome is characterized by the association of nephrotic syndrome and central nervous system anomalies. "Here, the authors report mutations in YRDC and the KEOPS component GON7 in Galloway-Mowat syndrome and determine the crystal structure of a GON7-containg subcomplex that suggests a role in KEOPS complex stability." (PMID 31481669, 2019). "Galloway-Mowat syndrome (GAMOS) is a group of rare hereditary diseases by the combination of early onset steroid-resistant nephrotic syndrome (SRNS) and microcephaly with brain anomalies caused by WDR73, LAGE3, OSGEP, TP53RK, TPRKB, GON7, WDR4 or NUP133 mutations." (PMID 36755238, 2023).
microcephaly (3 papers, 2019 to 2024). A congenital or acquired developmental disorder in which the circumference of the head is smaller than normal for the person's age and sex. "In addition to developmental delay, primary microcephaly was present in the two affected children of one family with YRDC mutations, whereas the affected child in the second YRDC family and all GON7-mutated individuals presented with post-natal microcephaly." (PMID 31481669, 2019).
GON7 also shares sentences with these, for which no sentence is quoted: cancer (1 paper); colon cancer (1); developmental delay (1); head and neck cancer (1); lung carcinoma (1); melanoma (1); nephrotic syndrome (1); ovarian carcinoma (1); Primary microcephaly (1); prostate carcinoma (1); tumor (1).